RNU4-87P (RNA, U4 small nuclear 87, pseudogene)
Gene: Small nuclear RNA gene on chromosome 4 (165,252,580 to 165,252,661, forward strand). Ensembl gene ENSG00000200974.
Homologues: Orthologues: chimpanzee U4 (99% identical), macaque U4 (96% identical), dog U4 (83% identical), guinea pig U4 (77% identical), tropical clawed frog U4 (74% identical), tropical clawed frog U4 (72% identical), tropical clawed frog U4 (71% identical), tropical clawed frog U4 (70% identical), tropical clawed frog U4 (67% identical), tropical clawed frog U4 (66% identical). Paralogues in human: RNU4-33P (99% identical), RNU4-42P (84% identical), U4 (84% identical), RNU4-6P (83% identical), RNU4-91P (83% identical), RNU4-36P (82% identical), RNU4-84P (82% identical), RNU4-12P (80% identical), RNU4-15P (80% identical), RNU4-40P (80% identical), RNU4-67P (80% identical), RNU4-79P (80% identical), and 80 more.